WT1 (WT1 transcription factor)
Diseases named in the same sentence as WT1 in open-access papers (continued):
Sharing a sentence is not in itself a finding about the gene and the disease.
Denys-Drash syndrome (51 papers, 2006 to 2026). "Specific pathogenic variants in the WT1 gene result in the following variable phenotypes: Frasier syndrome (FS), Denys-Drash syndrome (DDS), steroid-resistant nephrotic syndrome (SRNS), and disorders in genital development." (PMID 40332152, 2025). "Many phenotypic features found in the XY Wt1LoxP/GFP;Wt1Cre mice, such as gonadal dysgenesis and ambiguous genitalia, have been identified in XY humans with WT1 mutations, including in those with Denys-Drash syndrome or Frasier syndrome." (PMID 35704566, 2022). "As germline alterations, WT1 mutations are common in syndromic predisposition syndromes (e.g., Denys-Drash syndrome and WAGR syndrome), bilateral WT and WT with synchronous nephrogenic rests." (PMID 35911825, 2022). "Both heterozygous missense variants we identified in WT1 have been reported as pathogenic before with WT1 c.1315C>T, p.Arg439Cys identified in Denys-Drash syndrome and Meacham syndrome as well as in a Japanese patient with SRNS." (PMID 36245711, 2022). "It is caused by chromosome 11p13 deletions, including WT1 and neighboring genes, whereas Denys-Drash syndrome (DDS) is due to a dominant-negative WT1 mutation." (PMID 34638500, 2021). "Defects in WT-1 are the cause of multiple renal diseases, such as nephrotic syndrome type 4, Denys-Drash syndrome, and Frasier syndrome." (PMID 32774146, 2020). "R394W is located in the DNA-binding domain of WT1 and is the most common mutation described in Denys-Drash syndrome (DDS)." (PMID 30450160, 2018). "The Denys-Drash syndrome, caused by germ line mutations of WT1, shows the importance of WT1 for human renal and genital development." (PMID 29152069, 2017). "More recently, the Wt1+/R394W mice (a common WT1 missense mutation in Denys-Drash syndrome) has been shown to be subfertile due to defect in follicle development." (PMID 26358501, 2015). "In contrast, SRPK1 modulates alternative splicing of VEGF pre-mRNA, which leads to excessive angiogenesis in patients with Denys-Drash Syndrome harboring a mutation of the tumor suppressor gene WT1." (PMID 25581376, 2015). "Mutations in the WT1 gene are associated with glomerulosclerosis in patients of Denys Drash syndrome indicating the importance of this factor in the renal function in adulthood." (PMID 16684343, 2006). "Mutations in the WT1 gene can also lead to Frasier syndrome or Denys-Drash syndrome." (PMID 39600756, 2024). "For one thing, mutation of WT1 could induce idiopathic diffuse mesangial sclerosis and Denys-Drash syndrome, and depression of WT1 expression tended to trigger onset of crescentic nephritis and mesangial sclerosis." (PMID 31352863, 2019). "WT1 is originally identified as a tumor suppressor gene associated with the development of Wilms' tumors and is subsequently found to be mutated in patients with Denys-Drash syndrome (DDS)." (PMID 31583044, 2019). "The patient with a mutation of the WT1 gene was diagnosed as Denys-Drash syndrome." (PMID 28825592, 2018). "This is seen in patients with WT1 mutations, such as Denys Drash Syndrome." (PMID 23935865, 2013). "Heterozygous de novo mutations in WT1 cause Denys-Drash syndrome (DDS) and Frasier syndrome (FS)." (PMID 22693670, 2012). "WT1 mutation causes a variety of glomerular diseases, including Denys-Drash syndrome (DDS), Frasier syndrome (FS), and isolated steroid-resistant nephrotic syndrome (ISRNS)." (PMID 37576146, 2023). "The SRY activation is important for the development of testes and thus determines the male sex18; WT1 variants may thus cause impairment of proper male sex development, which also explains why the disorder of sex development in Denys-Drash syndrome is rather male specific." (PMID 35610319, 2022). "WT1 mutation could be analyzed only in one patient with Denys-Drash syndrome clinically." (PMID 28825592, 2018). "Whole exome sequencing identified a de novo heterozygous WT1 c.1384C > T; p.R394W mutation, which is classically associated with Denys-Drash syndrome (DDS)." (PMID 28720077, 2017).
Denys-Drash syndrome (continued). "WT1 is mutated in 94% of all Denys-Drash syndrome (DDS) patients, companied with the development of glomerular nephropathy involving glomerulosclerosis." (PMID 22693670, 2012). "In humans, WT1 gene mutations are responsible for two urogenital diseases: Denys-Drash syndrome (DDS) and Frasier syndrome." (PMID 18445271, 2008). "Denys-Drash syndrome (DDS) is caused by Wilms’ tumor gene 1 (WT1) gene mutations in exon 8 or 9, which encodes for a nuclear WT1 protein; this transcription factor plays an important role in the urogenital system development." (PMID 39445256, 2024). "Previously, these phenotypes were mainly attributed to missense variants in the DNA-binding/Zinc-finger domain (exon 8 and 9, Denys-Drash syndrome) and intron 9 (Frasier syndrome) of the WT1 gene, which was therefore referred to as the “hotspot” region." (PMID 39698353, 2024). "Significantly higher rates of kidney failure were found among patients with WAGR syndrome (WAGR), Denys-Drash syndrome (DDS), and those with associated male genitourinary (GU) anomalies, all related to constitutional WT1 pathogenic variants." (PMID 34608521, 2022). "Mutations in WT1 play a role in 46,XY DSD (i.e. FS, Denys-Drash syndrome, and WAGR-syndrome), and those found in FS consist of WT1 intron 9 splice-site mutations." (PMID 22815844, 2012). "Mutant WT1 proteins transcribed from the WT1 gene that contained the pathogenic variants found in Denys-Drash syndrome cases failed to activate the SRY promoter in a reporter gene assay, whereas the wild type WT1 protein was able to do so17." (PMID 35610319, 2022). "WT1 is an inhibitor of SRPK1 phosphorylation; Denys Drash Syndrome patients have a mutation in WT1, resulting in no inhibition of SRPK1 and an increased VEGF-A165/VEGF-A165b ratio." (PMID 30865689, 2019). "Constitutional deletions of WT1 at 11p13 is well established as the genetic basis for WAGR (WT aniridia genitourinary anomaly mental retardation), while germ line mis-sense mutations in WT1 are responsible for WT occurring as part of Denys-Drash syndrome." (PMID 22275972, 2008). "Additionally, the Wt1+/R394W germline mouse model has potential to develop Denys-Drash syndrome in a strain-dependent manner, leading to other non-hematopoietic morbidities." (PMID 30450160, 2018).
Frasier syndrome (49 papers, 2008 to 2025). Frasier syndrome is characterized by the association of male pseudohermaphrodism and glomerular nephropathy. "Whole-exome sequencing unveiled a novel variant, c.1447 + 6(IVS9)T > C, in the WT1 gene, and karyotypic analysis revealed 46, XY, aligning with the phenotypic presentation of Frasier syndrome (FS, OMIM#136680) associated with WT1 gene mutation." (PMID 40980126, 2025). "Frasier syndrome is generally attributed to a splice-site mutation in intron 9 of the WT1 gene, characterized by a delayed onset of kidney disease and an elevated incidence of gonadoblastoma." (PMID 40426774, 2025). "Frasier syndrome and Denys–Drash syndrome are disorders associated with the WT1 gene, sharing characteristics such as male pseudohermaphroditism, progressive nephropathy, and an increased risk of genitourinary malignancies." (PMID 40426774, 2025). "Nevertheless, it is worth noting that an altered ratio of KTS splice isoforms (i.e. WT1−KTS↑/WT1+KTS↓) causes Frasier syndrome, which is characterized by progressive glomerular nephropathy and male-to-female sex reversal in humans." (PMID 39359415, 2024). "Wilms tumor 1 (WT1; NM_024426) causes Denys–Drash syndrome, Frasier syndrome, or isolated focal segmental glomerulosclerosis." (PMID 38877226, 2024). "In patients with Frasier syndrome, heterozygous mutations in WT1 prevent the production of +KTS, resulting in higher amounts of -KTS variants." (PMID 37917714, 2023). "Patient 643 has Frasier syndrome, which is a genetic condition caused by a WT1 mutation that causes FSGS." (PMID 36940798, 2023). "Frasier syndrome, due to WT1 splicing pathogenic variant, has an intermediate rate of decline in kidney function and a much lower risk of WT." (PMID 34608521, 2022). "These case reports support expansion of the clinical spectrum of the kidney phenotypes associated with Frasier syndrome providing evidence of an association between WT1 mutation and an immune complex-related membranoproliferative glomerulonephritis." (PMID 35211794, 2022). "Intronic WT1 mutations are usually causative of Frasier syndrome with focal segmental glomerulosclerosis as the characteristic nephropathy." (PMID 35211794, 2022). "Frasier syndrome is characterized by male pseudohermaphroditism and progressive glomerulopathy due to a mutation in intron 9 of the WT1 gene that results in reduced WT1 (+KTS) splicing events." (PMID 28059119, 2017). "Mutations in some Frasier syndrome patients result in the predicted decrease of the WT1(+KTS) isoform and diminution of the WT1 (+KTS/-KTS) isoform ratio." (PMID 25617744, 2015). "Frasier syndrome, also caused by WT1 germline mutations, is associated with 46,XY CGD and involves focal and segmental glomerulosclerosis of the kidney." (PMID 24731683, 2014). "Mutations in the splice site of WT1 that change the normal +KTS/−KTS ratio of 60:40 to 40:60 lead to Frasier syndrome." (PMID 25258363, 2014). "For example, Frasier syndrome in humans is associated with XY sex reversal and caused by reduced expression of the Wt1 +KTS isoform." (PMID 22496664, 2012). "Evidence that the WT1(+KTS) isoform has important roles in podocyte function is provided by WT1 mutations in patients with Frasier syndrome cause a reduction in relative levels of the WT1(+KTS) isoform." (PMID 19652713, 2009). "WT1 mutations that lead to Denys-Drash syndrome and Frasier syndrome are each associated with nephrotic syndrome, renal failure, and intersex disorders, although only the former is commonly associated with Wilm's tumor." (PMID 19652713, 2009). "Similarly, detection of a heterozygous pathogenic variant in intron 9 of WT1 lead to the diagnosis of Frasier syndrome in a girl (case 67), who was then found to have 46 XY in karyotyping, complete sex reversal and gonadal dysgenesis." (PMID 37464296, 2023).
Frasier syndrome (continued). "Frasier syndrome (FS) is a rare inherited disorder characterized by gonadal dysgenesis and progressive nephropathy, resulting from mutations in the intron 9 splice donor site of the Wilms tumor 1 (WT1) gene." (PMID 36980135, 2023). "However, a WT1 mutation (IVS9+5G>A) that causes Frasier syndrome has also been linked to hypergonadotropic hypogonadism and increased serum levels of gonadotropins (LH and FSH) in patients." (PMID 25617744, 2015). "Frasier syndrome (FS) is characterized by gonadal dysgenesis with a high risk for development of GB as well as chronic renal failure in early adulthood, and is known to arise from a splice site mutation in intron 9 of the Wilms’ tumor 1 gene (WT1)." (PMID 22815844, 2012). "Denys–Drash (DDS) and Frasier syndromes (FS) are caused by WT1 gene mutations." (PMID 19066979, 2010). "In addition, aberrant splicing events—such as those caused by mutations in WT1 gene in Frasier syndrome—may alter isoform abundance, affecting several cell processes." (PMID 24573881, 2014). "On the other hand, Frasier syndrome, characterized by focal segmental sclerosis, delayed kidney failure and XY gonadal sex reversal, is associated with heterozygous point mutations in intron 9 that cause a shift in the ratio of WT1 isoforms (+/-KTS) towards the -KTS forms." (PMID 18445271, 2008). "WT1 gene mutation is also known to be the etiology for syndromic DSD such as Denys–Drash syndrome and Frasier syndrome." (PMID 39936125, 2025). "The clinical, pathological, and genetic findings in this patient are consistent with a WT1-related disorder, predominantly aligning with features of Frasier syndrome, while also exhibiting elements characteristic of Denys–Drash syndrome." (PMID 40426774, 2025). "Depending on the exon involved, pathogenic variants of the WT1 gene can lead to DDS (Online Mendelian Inheritance in Man database identifier; OMIM#194080) or Frasier syndrome." (PMID 40303223, 2025). "This case stands out for its complexity, particularly when compared to other reported WT1-related disorders, due to the considerable clinical and genetic overlap between Frasier syndrome (FS) and Denys–Drash syndrome (DDS)." (PMID 40426774, 2025). "Mutations in Wilms tumor 1 (WT1) gene cause several diseases characterized by renal and /or genital anomalies, such as Denys–Drash syndrome (DDS), Frasier syndrome (FS), and isolated focal segmental glomerulosclerosis (FSGS)." (PMID 32838737, 2020). "Another two cases of recurrent FSGS have been recently described: one had the NPHS2 mutation and the other had the WT1 mutation (IVS9 + 4C>T) and Frasier syndrome." (PMID 19066979, 2010). "The importance of WT1 in male sex determination has also been well-documented in the human since several diseases have been shown to be associated with WT1 mutations, such as DDS and Frasier syndrome." (PMID 18445271, 2008). "Mutations involving WT1 are typically seen, and several genetic syndromes such as Wilms Tumor Aniridia Genitourinary Anomalies Syndrome (WAGR), Denys-Drash, Beckwith-Wiedemann, and Frasier Syndrome have been implicated in children presenting with bilateral WT." (PMID 40630716, 2025). "WT1 mutations have also been linked to other congenital syndromes, including WAGR (WT, aniridia, genitourinary syndromes, and range of developmental delays) and Frasier syndrome, which are associated with a predisposition to WTs." (PMID 40890712, 2025). "Frasier syndrome is caused by altered ratios of WT1 isoforms (with and without the KTS insert), which modulate target gene expression patterns." (PMID 40493154, 2025). "Mutations in WT1 can cause many different diseases including non‐syndromic POI and syndromic POI such as Denys–Drash syndrome, WAGR syndrome, and Frasier syndrome." (PMID 34845858, 2022). "One unusual male patient carried the splice site pathogenic variant associated with Frasier syndrome that prevents formation of the +KTS isoform of WT1 but lacked any GU malformation." (PMID 34608521, 2022).
Frasier syndrome (continued). "Karyotype analyses and genomic sequencing revealed the patient had XY chromosomes but no causative mutations of Frasier syndrome in WT1 (data not shown)." (PMID 33094908, 2020). "This is not surprising given that the best known human WT1 mutation associated with sex reversal (Frasier syndrome) produces a shift in the WT1 +/-KTS ratio that favors the -KTS isoform." (PMID 18445271, 2008). "Interestingly, mutations in intron 9 of the WT1 gene, where alternative splicing to generate WT1+KTS and –KTS occurs, result in Frasier syndrome, including sex reversal and developmental defects in kidney and gonads." (PMID 25617744, 2015).
sarcoma (48 papers, 2010 to 2026). A usually aggressive malignant neoplasm of the soft tissue or bone. "High levels of WT1 expression was associated to the high grade of proliferation of cancer cells in the examined sarcoma tissue samples." (PMID 28107196, 2017). "Strong WT1 expression was associated with a better outcome in the group with high grade sarcoma (P = 0.025)." (PMID 25026998, 2014). "Thus, our method may have applications not only for gene fusions such as EWS-FLII1, EWS-ERG, EWS-FEV, and EWS- WT1 but also for other gene fusions which are commonly found in sarcomas and also somatic frameshift mutations." (PMID 36900411, 2023). "The expression of WT1 seems to be at most focal and weak in most sarcomas with KAT6B/A::KANSL1 fusion, and 50% of the analyzed cases were entirely negative, which would be unusual for LG-ESS." (PMID 39627614, 2025). "The Ewing sarcoma breakpoint region 1 gene fused with WT1 (EWSR1-WT1) gene fusion was detected in all patients." (PMID 34193155, 2021). "The WT1 peaks showed a marked enrichment for intergenic and intronic genomic locations consistent with other sarcoma fusion oncogenes’ occupancy at genomic enhancers." (PMID 32703985, 2020). "Of note, CIC-DUX4 translocation sarcomas have been reported to show WT1 staining in >90%, while BCOR-translocation sarcomas were reported to show strong staining of BCOR, BCL-2, cyclinD1, and TLE1 staining in most cases (each 80–90%)." (PMID 32204536, 2020). "Desmoplastic small round cell tumor (DSRCT) is a rare, aggressive, and poorly investigated simple sarcoma with a low frequency of genetic deregulation other than an Ewing sarcoma RNA binding protein 1 (EWSR1)-Wilm’s tumor suppressor (WT1) translocation." (PMID 30486883, 2018). "Immunohistochemical staining for CIC::DUX4 sarcomas is most notably positive for WT1 and CD99." (PMID 40599504, 2025). "ETV4 expression, along with at least focal WT1 expression is helpful in distinguishing CIC-rearranged sarcoma from its differential diagnosis, although some challenges maybe encountered in optimizing the ETV4 antibody." (PMID 40722508, 2025). "Although the role of WT1 in sarcoma biology remains unclear, work from our laboratory, and from others, has implicated WT1 in the regulation of angiogenesis." (PMID 24810959, 2014). "Previous studies strongly indicate that the non-mutated wild-type WT1 gene is involved in tumorigenesis of various types of human bone and soft-tissue sarcomas including OS and that it is expressed at protein level in a larger number of highly proliferating cancer cells." (PMID 28107196, 2017). "The distinct diagnostic features for these tumors included positive GFAP and Olig-2 expression, negativity of WT-1 and reticulin, and a methylation profile incompatible with conventional MC CIC-rearranged sarcomas." (PMID 38926750, 2024). "Biopsy revealed a primitive round cell sarcoma with positive nuclear expression of DUX4 and WT1, suggestive of a CIC-rearranged sarcoma." (PMID 38436779, 2024). "These tumors displayed morphologic features similar to bona fide CIC-DUX4 sarcomas, namely lobulation, focal spindling, myxoid changes, distinct nucleoli, and positive ETV4 and WT1 immunohistochemical stains." (PMID 34898574, 2021). "The present study shows for the first time that WT1 is a highly sensitive immunomarker for DFSP, suggesting its potential use in distinguishing this sarcoma especially from cellular dermatofibroma and deep fibrous histiocytoma." (PMID 33445443, 2021). "The results suggest that WT1, calretinin and ETV4 may be useful markers for the differentiation of CIC rearrangement sarcoma and other small round cell tumors." (PMID 40255429, 2025).